RNU6-19P (RNA, U6 small nuclear 19, pseudogene)
Synonyms: RNU6-19
Gene: Small nuclear RNA gene on chromosome 15 (65,553,081 to 65,553,187, reverse strand). Ensembl gene ENSG00000207449.
Homologues: Orthologues: guinea pig U6 (94% identical), macaque U6 (91% identical), rabbit U6 (91% identical), pig U6 (88% identical). Paralogues in human: RNU6-12P (97% identical), RNU6-13P (97% identical), RNU6-31P (97% identical), RNU6-32P (97% identical), RNU6-1 (96% identical), RNU6-1060P (96% identical), RNU6-15P (96% identical), RNU6-17P (96% identical), RNU6-18P (96% identical), RNU6-2 (96% identical), RNU6-3P (96% identical), RNU6-4P (96% identical), and 1285 more.